MMP9 (matrix metallopeptidase 9)
Diseases named in the same sentence as MMP9 in open-access papers (continued):
Sharing a sentence is not in itself a finding about the gene and the disease.
brain edema (continued). "Thus, it is reasonable to conclude that BBB disruption during the course of 1,2-DCE-induced brain edema could result from excessive MMP-9 mediated through activation of the p38 MAPK/ NF-κB signaling pathway." (PMID 31461951, 2019). "Wang and colleagues observed that escin reduced the levels of matrix metalloproteinase-9 (MMP-9), TNF-α, COX-2, and PGE2 in the brain in their experimental model of poisoning-related brain edema." (PMID 39334789, 2024). "We previously reported that expression of matrix metalloproteinase-9 (MMP-9) mRNA and protein was upregulated during 1,2-dichloroethane (1,2-DCE) induced brain edema in mice." (PMID 31461951, 2019). "Consistent with our previous studies, MMP-9 was overexpressed and BBB was disrupted during the course of 1,2-DCE-induced brain edema in mice." (PMID 31461951, 2019). "Findings from our previous work have revealed that the p38 MAPK signaling pathway was activated and involved in NF-κB activation and MMP-9 overexpression during the course of 1,2-DCE-induced brain edema in mice." (PMID 31461951, 2019). "The present study demonstrated that ectogenic PROG noticeably inhibits MMP-9 mRNA expression, and reduces the number of MMP-9-positive cells and the MMP-9 content in the cerebral cortex, thereby reducing BBB damage and cerebral edema." (PMID 23935758, 2013). "In addition, diacerein ameliorates hyperammonemia induced cerebral edema and maintains BBB integrity through modulation of TLR4/AQP4/MMP-9 axis." (PMID 39556255, 2024). "Moreover, we further demonstrated that MMP-9 overexpression and BBB disruption during the course of 1,2-DCE-induced brain edema were mediated through the p38 MAPK/NF-κB signaling pathway." (PMID 31461951, 2019). "As overexpression of MMP-9 can result in breakdown of BBB in traumatic, hemorrhagic, and ischemic brain injury, studying the regulatory pathways is necessary for uncovering the mechanisms of 1,2-DCE induced brain edema." (PMID 30087244, 2018). "MMP-9 and LCN-2 released from activated neutrophils might contribute to the leakage of the blood-brain barrier and subsequent brain edema." (PMID 28409125, 2017). "Since overexpression of MMP-9 can result in brain damage, studying the regulatory pathways of MMP-9 expression is necessary for identifying new therapeutic targets in the treatment of 1,2-DCE induced brain edema." (PMID 28769771, 2017). "In the current study, we determined whether PROG alleviates BBB damage and cerebral edema by controlling the expression of AQP-4 and MMP-9." (PMID 23935758, 2013). "The accumulated results in our laboratory have demonstrated that up-regulated expression of MMP-9 and AQP4, and down-regulated expression of tight junction proteins, such as ZO-1 and occludin could be induced by 1,2-DCE poisoning during the course of brain edema." (PMID 29410610, 2018). "We obtained preliminary conclusions from serum indicators of clinical patients that miR-7-5p may affect brain edema, but it does not affect MMP-9, ZO-1, occludin, IL-6, TNF-α, NLR, and CRP expression to affect the formation of brain edema." (PMID 33392188, 2020). "In keeping with the role of MMP-9 in hastening BBB disruption and resultant injury, a non-significant increase in MMP-9 levels was observed in those tPA-treated patients that developed severe brain edema." (PMID 26973468, 2016).
cerebral infarction (39 papers, 2012 to 2025). An ischemic condition of the brain, producing a persistent focal neurological deficit in the area of distribution of the cerebral arteries. "Third, when cerebral infarction occurs, inflammatory reactions around the infarct cause chemotactic neutrophil degranulation, and MMP‐9 enters the blood circulation and is highly expressed in the peripheral blood." (PMID 35620813, 2022). "Studies have confirmed that MMP-9 gene polymorphism is associated with the increased prevalence of cerebral infarction." (PMID 34260532, 2021). "MMP-2/MMP-9 aggravates BBB dysfunction caused by cerebral infarction by degrading ZO-1 and claudin-5, all TJ proteins." (PMID 33584203, 2020). "The association between MMP-9 and cerebral infarction was also low, but were analyzed with few events during follow-up." (PMID 26389803, 2015). "Moreover, cerebral infarct size is reduced in mice deficient in MMP-9 or after treatment with MMP inhibitor; this effect was associated with reduced degradation of the MMP-9 substrate ZO-1 as compared to WT mice." (PMID 23565108, 2013). "Through bioinformatics analysis, we identified key targets associated with cellular senescence and circadian rhythm in cerebral infarction, specifically CREBBP, FOS, CDK4, MMP9, PTEN, and HIF1A." (PMID 40629591, 2025). "Pathological research on cerebral infarction has found that the serum levels of Matrix Metalloproteinase-9 (MMP-9) in patients are significantly higher than those of other types of MMPs." (PMID 40869300, 2025). "Positive studies have demonstrated that sparse-dense wave electroacupuncture with a frequency of 2/100 Hz can advance the peak of MMP-9 expression in rats after brain infarction." (PMID 38536776, 2024). "This study found that the serum MMP-9 level in patients with cerebral infarction was significantly higher than that in the normal control group at different stages of early-onset, and the serum MMP-9 level was still significantly higher at 7 days after onset." (PMID 35083027, 2022). "In the early stage after cerebral infarction, neutrophils adhere to the cerebrovascular endothelium and release MMP‐9." (PMID 35620813, 2022). "Matrix metalloproteinases are a group of zinc-dependent proteases, and MMP-9 is one of the gelatinase groups, which plays an important role in the occurrence and development of cerebral infarction." (PMID 35083027, 2022). "The higher the serum CRP level, the more likely the patient is to develop a cerebral infarction The results displayed that Huoxue Tongluo prescription effectively downregulated MMP-9, Hcy, and CRP levels." (PMID 35399851, 2022). "In this study, vx-765 treatment enhanced the expression levels of TIMP-1 and TIMP-2 but reduced the expression levels of MMP-1, MMP-2, MMP-3, and MMP-9 proteins after cerebral infarction." (PMID 33584203, 2020). "Related clinical studies have found that the expression of MMP‐9 in the infarcted area and its surrounding area significantly increased after cerebral infarction in patients." (PMID 31566928, 2019). "The administration of neutralizing MMP‐9 monoclonal antibody significantly reduced cerebral infarction." (PMID 31566928, 2019). "MMP-9 expression is the main factor contributing to the progression of neuronal apoptosis and the subsequent brain infarct." (PMID 27642277, 2016). "The Hazard Ratios for the composite measure are somewhat lower than for CHD incidence when evaluated as its own entity suggesting that MMP-9 is a more relevant marker for CHD incidence than cerebral infarction." (PMID 26389803, 2015). "At patient admission to the hospital, plasma concentrations of MMP-9 are predictive of cerebral infarct volume on magnetic resonance imaging and are correlated with stroke lesion growth, even after thrombolysis administration." (PMID 25029344, 2014). "Plasma concentrations of MMP-9 are also related to cerebral infarction size, neurological outcomes and haemorrhagic transformation, especially after fibrinolysis." (PMID 25029344, 2014).
cerebral infarction (continued). "These circulating neutrophils are a source of MMP-9, a protease which is particularly present in and around cerebral microvessels after a brain infarct." (PMID 24885160, 2014). "Many methalloproteinases showed highly altered expression, including MMP2 and MMP7 at 3 d after cerebral infarct, as well as MMP9 and MMP12 in the acute (24 h) phase." (PMID 23284893, 2012). "Vafadari B believed that MMP-9 played a significant role in the pathological process of secondary brain injury after cerebral infarction and may be a new biological indicator for predicting cerebral infarction." (PMID 35399851, 2022). "The difference was statistically significant, suggesting that MMP-9 could be used as a biomarker for predicting cerebral infarction." (PMID 35083027, 2022). "Moreover, recent research indicates that MMP-9 is an effective target for treating cerebral infarction, and the drugs that inhibit MMP-9 expression could maintain the integrity of the BBB and reduce cerebral edema." (PMID 40869300, 2025). "Brain infarction and edema were assessed, and Western blot analyses were conducted to examine the expression levels of aquaporin-4 (AQP4), metalloproteinase-9 (MMP-9), and the neurovascular tight-junction protein ZO-1 upon sacrifice." (PMID 39457496, 2024). "A review by Turner & Sharp (2016) concluded that the sequence of MMP‐9 is involved in the blood brain barrier (BBB) destruction and repair after cerebral infarction." (PMID 35620813, 2022). "Previous studies have found that circulating MMP-9 and MCP-1 levels were closely related to the opening of collateral circulation after cerebral infarction." (PMID 34489737, 2021). "Several matrix-methaloproteinases such as MMP2, MMP7, MMP9 and MMP12, were up-regulated after cerebral infarct." (PMID 23284893, 2012). "l-borneol can also inhibit neuronal apoptosis and enhance the stability of neovascularization by inhibiting the levels of ACE, MMP9, HIF1α, TGF-β1 and Tie2, thereby improving the neurological deficit in ischemic rats, reducing the rate of cerebral infarction, and exerting neuroprotective effects." (PMID 33746762, 2021). "Matrix metalloproteinase (MMP)-9, also called gelatinase B, is the MMP with the highest expression after hypoxic-ischemic changes and is closely related to the occurrence and development of cerebral infarction." (PMID 34987460, 2021). "Cox regressions of MMP-9 in relation to a composite measure of CHD-events and cerebral infarction." (PMID 26389803, 2015). "All HR’s for MMP-9 were non-significant in those regressions, ranging from HR = 0.97 to 1.11 for cerebral infarction and from HR = 0.90 to 0.97 for fatal events (data not shown)." (PMID 26389803, 2015). "At 24 h after occlusion, BBB permeability, hemispheric enlargement, collagen and laminin degradation, and cerebral infarction were increased in both WT and MMP-9 KO treated animals as compared with non-treated animals." (PMID 23565108, 2013). "On the other hand, an increase in serum concentrations of TIMP-1, but not MMP-9 of the MMP-9/TIMP-1 ratio has been reported in patients with central nervous disorders, such as cerebral infarction, cranial hemorrhage, traumatic brain injury, hemolytic-uremic syndrome, and HHV-6 encephalitis." (PMID 36670630, 2022).
head and neck cancer (39 papers, 2009 to 2025). A primary or metastatic malignant neoplasm affecting the head and neck. "Generally MMP-9 has been associated with aggressive head and neck cancers, but novel studies have shown that it acts as a protective molecule during carcinogenesis and metastasis." (PMID 23365550, 2013). "Bioinformatics analysis showed that MMP-9 was associated with survival and tumour function in patients with head and neck cancer, suggesting that MMP-9 may be a saliva-based noninvasive diagnostic biomarker and a prognostic therapeutic target for OSCC." (PMID 39911325, 2025). "In tumors with a moderate MMP-9 expression (e.g., prostate, pancreatic, and head and neck cancers), nanoprobes and other diagnostic tools can assess MMP-9 levels to guide personalized strategies, and MMP-9-targeted nanomedicines may still impede the disease progression." (PMID 40284474, 2025). "We validated these data in patients with head and neck cancer and identified bacterially colonized intratumoral niches that were enriched for mesenchymal tumor cells and neutrophils expressing NE and MMP-9." (PMID 40155451, 2025). "A study on head and neck carcinoma reported that rhIL-8 enhanced MMP9 expression in cancer cells; however, we consider that the response to rhIL-8 in vitro differs among cell types." (PMID 37296952, 2023). "The activation of ligand-receptor EGF-EGFR complex has been related to EMT and MMP9 in head and neck carcinoma and salivary adenoid cystic carcinoma." (PMID 36146635, 2022). "Recent research has suggested that the galectin-7-TCF3-matrix metallopeptidase (MMP-9) axis is a key regulator for Tid1-suppressed metastasis in head and neck cancer cells." (PMID 33233689, 2020). "Previously, several studies suggested that MLT inhibited the gene expression of MMP-9 in head and neck cancers, which is majorly responsible for metastasis." (PMID 32545820, 2020). "Even though this study does not specify the degradation of MMP9 mRNA by TTP, it is very plausible as MMP9 has been shown to be regulated by TTP in an direct manner in head and neck cancer." (PMID 31623614, 2019). "Mounting evidence has indicated that the inhibition of MMP-2 and MMP-9 activity reduces cancer cell metastasis in head and neck cancer." (PMID 29163852, 2017). "Previous studies also mentioned that melatonin inhibited the gene expression of MMP-9 in head and neck cancers." (PMID 29163852, 2017). "The study of melatonin-regulated head and neck cancer metastases has demonstrated that melatonin targeted the ERK/JNK pathways to reduce MMP-9 transcription and cancer cell invasion through modulating histone acetylation and SP1 activation." (PMID 29163852, 2017). "Other reports suggested that endothelial growth factor (EGF)-induced PTX3 production through the activation of the PI3K/Akt and NF-κB pathways increased MMP-9 and fibronectin expression in head and neck cancer cell metastasis." (PMID 27377307, 2016). "PTX3 can also regulate head and neck cancer cell metastasis by modulating the expression of fibronectin and MMP-9, in which contributes to NF-κB-promoted tumor metastasis." (PMID 27377307, 2016). "It is interesting to note that EGFR which is generally overexpressed in head and neck cancer can induce expression of MMP-9 and leads to the activation of the Raf-MEK-ERK signal transduction pathways which in turn can activate the c-Jun transcription factor." (PMID 26581505, 2015). "Previous studies of head and neck cancers have discovered that MMP-9 plasma concentrations correlate with disease stages of the cancer and MMP-8 plasma levels correlate with T-status, N-status and disease staging." (PMID 25423087, 2014). "For example, in salivary gland myoepithelial carcinoma, MMP-9 expression predicts a better overall survival, and in regional metastases of head and neck cancers, MMP9 gene expression was decreased." (PMID 23365550, 2013).
head and neck cancer (continued). "Additionally, studies among special populations such as head and neck cancer patients confirm that combining aMMP-8 and MMP-9 enhances the prediction of disease progression, underscoring the utility of multi-marker approaches for precision diagnostics." (PMID 41300956, 2025). "In our group, we have shown MMP-9 to be one critical protease for head and neck cancer invasion." (PMID 36674806, 2023). "MMP-9 in head and neck carcinoma is associated with shortened relapse-free and cause-specific survival, implying that MMP-9 has a role in tumor progression of head and neck carcinomas." (PMID 36674806, 2023). "In a clinical context MMP2 and MMP9 overexpression may be helpful markers in diagnosing head and neck cancer metastasis." (PMID 28963552, 2017). "As activated AKT and NF-κB (p65) could promote MMP-9 upregulation in head and neck cancers, we hypothesized that the miR-744-3p modulated MMP- 9 expression in LSCC." (PMID 27533461, 2016). "In order to comprehensively recognize the role and potential mechanism of the COL1A1, IL1A, MMP9, and FN1 genes in the prognosis of head and neck cancer, we constructed a miRNA-related regulatory network in the current study." (PMID 39065771, 2024). "MLT targeted the ERK/JNK pathways to reduce MMP-9 transcription and cancer cell invasion through modulating histone acetylation and SP1 activation in head and neck cancer." (PMID 32545820, 2020). "In numerous reports regarding head and neck cancers, the present correlations are emphasized between the changes in the expression of MMP-2, MMP-9, TIMP-1, and TIMP-2 with tumor progression or its clinical stage." (PMID 31223594, 2019). "Co-expression analyses indicated that SPP1 was co-expressed with MMP9, ARPC1B, and APP in head-neck cancer." (PMID 31849319, 2019). "For head and neck cancers, MMP-1, MMP-2, MMP-9 and membrane type-1 MMP were constantly observed overexpressed in the tumor tissues and were considered associated with the development and progression of cancer." (PMID 28427180, 2017). "For head and neck cancers, MMP-1, MMP-2, MMP-9 and membrane type-1 MMP have been found overexpressed in the tumor tissues and been associated with cancer progression." (PMID 25423087, 2014). "Direct co-culture between cancer cells and mesenchymal stem cells has been reported to have led to MMP9 upregulation in prostate and head and neck cancer cells, but not in indirect co-culture." (PMID 37296952, 2023). "There were also reports that MMP-9 expression did not correlate with tumor and lymph node stages but correlated as a prognostic factor for unfavorable survival in head and neck carcinoma." (PMID 33735248, 2021). "The results showed that SPP1 was over-expressed in patients with head-neck cancer, and the top 3 genes co-expressing with SPP1 were Matrix Metallopeptidase 9 (MMP9), Actin Related Protein 2/3 Complex Subunit 1B (ARPC1B) and Amyloid Beta Precursor Protein (APP)." (PMID 31849319, 2019). "Indeed, using recombinant human IL-8 as a treatment of head and neck cancer cells, their Western blot analyses revealed a decrease in the expression of E-cadherin and an increase in the expression of MMP2, MMP9, and vimentin compared to the untreated conditions." (PMID 37628994, 2023).